APP (amyloid beta precursor protein)
Diseases named in the same sentence as APP in open-access papers (continued):
Sharing a sentence is not in itself a finding about the gene and the disease.
amyloid (continued). "Given that activation of glial cells in AD and in AD mouse models may be initiated by Aβ peptides, it is possible that reduced gliosis in perinatally choline-supplemented APP.PS1 mice is secondary to the amelioration of the amyloidosis seen in these animals." (PMID 28103298, 2017). "Therefore, we can determine that the cerebral chronic diabetic condition promotes the metabolism of APP during amyloidosis, which subsequently leads to the generation and deposition of Aβ." (PMID 28467789, 2017). "Most recently the gantenerumab Aβ antibody was shown preferentially to bind aggregated brain Aβ and in APP/PS-1 mice, to reduce or halt Aβ plaque formation; however, the Phase 3 clinical trial, in early stage symptomatic patients with evidence of amyloid, was halted in December 2014." (PMID 27129593, 2016). "Therefore, we can infer that hyperglycemia exposure promoted the cerebral processing of APP during amyloidosis and attenuated Aβ clearance, which subsequently resulted in SP formation in the Pdx1+/−/APP/PS1 mouse brains." (PMID 27406855, 2016). "In addition to the behavioral experiments, we analyzed the amyloid plaque pathology in the APP/PS1 and APP/PS1-BDNF+/−-mice and observed a comparable plaque density in the two genotypes." (PMID 25852506, 2015). "Bexarotene has also been reported to reduce amyloid plaque and improve mental function in the APP/PS1 Alzheimer's mouse model, with clinical trials ongoing to determine whether this will translate to man." (PMID 26451138, 2015). "To further confirm the effect of TRPC6, we examined whether TRPC6 could reduce amyloid plaque in APP/PS1 mice with another genetic background." (PMID 26581893, 2015). "Additionally, the in vivo activation of Wnt signaling, with a mimetic peptide of Wnt-5a, rescues memory loss and improves synaptic dysfunction in APP/PS1-transgenic mice, a model the amyloid pathology of AD." (PMID 26124704, 2015). "Differences in hemodynamic read-outs might arise from the different transgenic APP mouse strains used in the studies with differences in onset and severity of amyloid pathology, and a different degree of vascular involvement." (PMID 26834622, 2015). "To summarize, amyloidosis, and not age, was associated with a constitutive change in α- to β- processing of APP among individuals." (PMID 24646516, 2014). "Interestingly, regular treatment of TgCRND8 APP transgenic mice with baicalein exacerbated the amyloid plaque burden, APP metabolism and Aβ production." (PMID 24671102, 2014). "In order to determine the effects of age and amyloidosis on the APP processing pathways, APP metabolites from a single CSF time-point at the onset of the study (between 8:00 A.M. and 10:00 A.M.)were compared among three participant groups: YNC, Amyloid−, and Amyloid+." (PMID 24646516, 2014). "Oleic acid reduces APP gene expression, and prevents amyloidosis in a rodent AD model." (PMID 24956173, 2014). "They found that, even though the amyloid pathology occurred as early as 3-month age in APP/PS1 mice, the deviation of BMD and microarchitecture could not be found until 9 months old." (PMID 25152713, 2014). "Furthermore, APP mRNA is upregulated by IL-1, an inflammation cytokine, further promoting amyloidosis and reinforcing a self-perpetuating cycle." (PMID 25400539, 2014). "The examination of the amyloid pathology with super-resolution microscopy permitted us to further reveal a clear separation of the subcellular location of Aβ-immunoreactivity from that of APP/CTFs." (PMID 24903713, 2014). "Interestingly, therapeutic application of the PPARγ agonists, pioglitazone, has been demonstrated to skew microglia from M1 to the M2 phenotype, reduce amyloid plaque burden, and improve cognitive deficits in the APP/PS1 mouse model of AD." (PMID 24244499, 2013).
amyloid (continued). "An increase in BACE1 level in plaque-associated dystrophic presynaptic terminals, in conjunction with APP accumulation in these neuritic dystrophies, may elevate local peri-plaque Aβ generation and exacerbate the progression of amyloid pathology in AD." (PMID 23820808, 2013). "BACE1 and APP accumulate in presynaptic dystrophies surrounding amyloid plaques, implying a feed-forward mechanism of Aβ generation that may exacerbate AD pathogenesis." (PMID 23820808, 2013). "In the APP-tg mouse immunoreactivity for ferritin light-chain, the iron storage isoform, was initially distributed throughout the brain and as the disease progressed accumulated in the core of amyloid plaques." (PMID 24252754, 2013). "Amyloid plaques are composed of aggregated amyloid-β peptides, derived from sequential proteolytic processing of the amyloid-precursor protein (APP), a type-I transmembrane protein with a large extracellular N-terminal domain and a short intracellular C-terminal tail." (PMID 24575399, 2013). "One of the patients characterized, a 65-year old without an additional copy of APP, did not have dementia or indication of amyloid accumulation when assessed by brain imaging, supporting a causative role for APP overexpression in neuropathology in DS." (PMID 22481915, 2012). "Recently, it was reported that vaccination of Tg mice with a 13 residue random sequence peptide derived from the carboxyl terminus of pABri (polymerized British amyloidosis peptide) related peptide reduces amyloid pathology and preserves cognitive function in APP/PS1 transgenic mice." (PMID 22866920, 2012). "The Tg APP model parallels the amyloidosis of the neurologic condition." (PMID 22248049, 2012). "The present study was performed to directly explore the effects of collagen-induced rheumatoid arthritis (CIA) on amyloid plaque formation, microglial activation, and microvascular pathology in the cortex and hippocampus of the double transgenic APP/PS1 mouse model for AD." (PMID 22029666, 2011). "Aβ burden, microglia/macrophages, and cerebral vascular pathology were investigated in APP/PS1 mice 4 months after the injections of CII in CFA to determine whether RA directly modulates amyloidosis and microvascular pathology in AD." (PMID 22029666, 2011). "The presence of HSP47 in amyloid deposits could be related to a role of this protein in amyloidogenic cleavage of APP and/or in the deposition of Aβ or it could simply reflect a secondary, bystander involvement." (PMID 21829458, 2011). "Another DbTg strain of mouse which over-expresses both the 695 amino acid isoform of human amyloid precursor protein (APP) with K670N and M671L mutations (APP695SWE mice) and the A246E mutation in PS1 (PS1A246E) has much more aggressive amyloidosis and plaque deposition than the APP695SWE mice." (PMID 20630068, 2010). "Our aim was to develop an inbred APP transgenic rat line with high APP expression in the brain, as we believe this may be one of the important prerequisites for producing amyloid pathology in rat models of AD." (PMID 18302776, 2008). "Interestingly, Singer and colleagues used RNA interference (RNAi) to silence BACE1 and demonstrated that a partial reduction in BACE1 can improve amyloid neuropathology including the deposition of Aβ, alongside cognitive deficits in APP Tg mice." (PMID 18005427, 2007). "In the present work we confirmed that passive anti-amyloid immunotherapy can reverse spatial learning deficits in APP-transgenic mice and that this benefit of immunotherapy is retained, even in aged mice (26 and 28 months old at testing) with long-established amyloid pathology." (PMID 15588287, 2004). "Although MG-induced pathology in wild-type mice reproduces key Alzheimer-like phenotypes, transgenic models (e.g., 5xFAD or APP/PS1) featuring genetically driven amyloid or tau pathology would further validate whether PG remains effective across broader AD mechanisms." (PMID 41516384, 2026).
amyloid (continued). "In summary, we hypothesise that amyloidosis might be a common pathophysiological process underlying the neurological disorders of CM and AD, most likely initiated by parasite-induced co-upregulation of APOE and APP in the cerebral tissues." (PMID 39023792, 2025). "Although mouse strains like TASD or J20, combining multiple APP mutations, demonstrate more aggressive AD‐like pathology, these models still reflect primarily amyloid pathology rather than the full spectrum of AD (also including tauopathy, neuroinflammation, and synaptic dysfunction)." (PMID 40420360, 2025). "Besides, coptisine could decrease the activation of microglia and astrocytes, reduce amyloid plaque formation, and ameliorate impaired cognition of APP/PSI mice." (PMID 40160459, 2025). "To determine whether an aberrant pattern of compartment-specific gain and loss might be common to other amyloidosis models, we selected Tg2576 mice, with overexpression of a human variant of APP carrying the Swedish mutations without additional PS1." (PMID 39262788, 2024). "Additionally, infusion of IGF2 in the APP.PS1 mouse model of AD ameliorated amyloidosis." (PMID 38315685, 2024). "Unlike APΔE9 mice where only APP and presenilin mutations are driven to express, 3xTg mice also express tau P301L transgene, thus these mice are valuable for studying the impact of both amyloid and tau pathology." (PMID 38476461, 2024). "Therefore, we can conclude that human microglia carrying either APP or PSEN1 ADAD mutations in isolation are not sufficient to cause amyloid pathology in the mouse brain." (PMID 38473822, 2024). "Therefore, further investigations are warranted to find novel pathways and molecular mechanisms that reduce Aβ levels either by APP processing enzymes or other multifunctional enzyme systems, including different degradation pathways, to prevent amyloidosis in LOAD." (PMID 39000011, 2024). "Here, we tested whether altered hippocampal activity measured by immediate-early gene (IEG) expression precedes broader synaptic changes in adolescent hippocampal CA1 pyramidal neurons using two different mouse models of amyloidosis, APPSwe/PS1dE9 (APP/PS1) and APPSwe (Tg2576)." (PMID 39262788, 2024). "This inconsistency may be caused by the fact that PSEN-1 is involved in both amyloidosis and non-amyloidosis pathways of APP, and less is known about other pathophysiological functions of this protein." (PMID 36774494, 2023). "Moreover, recent studies in the APP-KI (amyloid-beta precursor protein-knock in) mice show that GABAergic neurons in area CA1 contribute to 30% of amyloid plaque load, highlighting the bidirectional relationship between GABAergic interneurons (INs) and AD pathology." (PMID 37841892, 2023). "In agreement with the observations made in macrophages, our results demonstrate for the first time that 33i treatment increases the ability of microglia to engulf Aβ providing an additional mechanism that could contribute to the amelioration in amyloid pathology observed in 33i-treated APP/PS1 mice." (PMID 37698780, 2023). "When mutant APP expression is suppressed after the onset of amyloid pathology and cognitive deficits, a rapid improvement in cognitive performance is observed, accompanied by a large decrease in levels of full‐length APP, soluble APP ectodomains, and APP C‐terminal fragments." (PMID 37750482, 2023). "In the APP/PS1 model of amyloidosis, studies at 3-, 6- and 24-months of age (corresponding in this model to pre-symptomatic stage, onset and overt stages of pathology, respectively) pointed to the absence of dysbiosis at 3 months whereas dysbiosis was manifest in 6-months old APP/PS1 mice." (PMID 35248147, 2022). "Specifically, APP’s fold change (X ̄5XFAD/X ̄WT) as time progresses goes from 2.73 at 3 months to 3.50 at 6 months and 5.59 at 9 months revealing a temporal accumulation of both APP and Aβ in 5XFAD mice which mimics the increased amyloid burden characteristic of human AD." (PMID 35944844, 2022).
amyloid (continued). "Additionally, caspase 3 is involved in the cleavage of APP, so it could contribute to Amyloid pathology as well." (PMID 36275000, 2022). "Hence, the presence of extracellular amyloid plaques might be a prerequisite for enhanced neurofibrillary tangle formation in transgenic mice co-expressing human mutant APP and Tau." (PMID 34069029, 2021). "Since AMY/CTR complexes are localized on microglia, depletion of these target receptors for Aβ could attenuate the amyloid-induced neuroinflammation, including the cytokine release that is known to upregulate APP processing and thereby increase the rate of Aβ generation." (PMID 34312771, 2021). "In addition to tau phosphorylation, these kinases are also involved in APP processing also, e.g., GSK3, especially GSK3α, promotes Aβ formation from APP offering new approach, that inhibition of GSK3α might attenuate amyloid plaques and NFT formation." (PMID 34572312, 2021). "APP gene is targeted by three SCFAs; a total of 8 (out of 12) AD phenotypes (abnormal long-term potentiation, abnormal synaptic transmission, amyloid beta deposits, amyloidosis, astrocytosis, gliosis, microgliosis, and tau protein deposits) are associated with three SCFAs." (PMID 34670619, 2021). "Quantification of the hippocampal amyloid burden in experimental and control groups also showed that animals injected with Aβ−containing cattle brain homogenate doubled the regular amount of Aβ (0.11 ± 0.02 vs. 0.05 ± 0.01%) found in the hippocampus of APP/PS1 at this age." (PMID 35173603, 2021). "Taken together, it seems that amyloid induces tau aggregation and accumulation in the dendritic mitochondria and subsequently may alter synapse function, thus, contributing to accelerate cognitive decline in APP/PS1 mice." (PMID 34769380, 2021). "Moreover, overexpression of CCL2 driven by GFAP promoter in APP/CCL2 mice enhanced amyloidosis, increased microglial Iba-1immunoreactivity, and decreased cognition while APP/PS1/CCL2 null mice also displayed increased levels of Aβ oligomers and worsening of cognitive dysfunction." (PMID 32508844, 2020). "Thus, similar changes in the total Aβ-positive area and plaque morphology were observed in the double tg mice based on distinct types of APP tg mice, i.e., a substantial decrease in the diffuse-type Aβ plaques and the appearance of middle-sized compact Aβ plaques occasionally with amyloid cores." (PMID 33287899, 2020). "For example, it has been reported that, similar to CX3CR1 deficiency, amyloid precursor protein/presenilin-1 (APP/PS1) mice lacking CX3CL1 showed reduced amyloid pathology, and expression of obligate sFKN in this context did not improve or exacerbate this effect." (PMID 32410624, 2020). "Thus, we investigated whether apoE can be found in microglia in the setting of amyloidosis, specifically in the APP/PS1–21 model which develops Aβ deposition in amyloid plaques beginning at 6–8 weeks of age." (PMID 31623648, 2019). "Thus, the Tet-Off APP mouse model could be an interesting and useful tool while used as a mature-onset model to study the amyloid aspect of sAD for further understanding the AD mechanisms." (PMID 31727182, 2019). "Thus, the Tet-Off APP mouse model could be a powerful tool while used as a mature-onset model to shed light into amyloidosis mechanisms in AD." (PMID 31727182, 2019). "While further experiments are needed to shed light on the mechanisms underlying the early hypersynchronisation of neuronal networks in AD pathology, the inducible Tet-Off APP mouse model of amyloidosis could be an interesting and useful tool when used as mature-onset." (PMID 31727182, 2019). "AAV vectors encoding BRI-Aβ cDNAs, fusions between human Aβ peptides and the BRI protein (known to be associated with amyloid deposition in British familial dementia), are able to promote high-level expression of Aβ peptide in the absence of APP overexpression." (PMID 31685865, 2019).
amyloid (continued). "Moreover, blocking of the Nogo/NgR pathway promoted expression of CD36 which might increase clearance of Aβ and further ameliorate amyloid load in APP/PS1 mice." (PMID 30029608, 2018). "The levels of APP and PS1 overexpression vary between amyloid mouse models because of different promoters used and local effects of genomic insertion sites, so we started by quantifying the expression of transgenic APP and PS1 relative to the endogenous mouse proteins." (PMID 30315100, 2018). "Taken together, CSP could mitigate amyloid pathology and inflammatory reaction in APP mice." (PMID 29535835, 2018). "The degree of amyloidosis in the APP/PS1 knockin model is substantially lower than attained by APP transgenic mice, and it is possible that had we used a stronger or more ubiquitous tTA driver we might have observed an effect outside of the entorhinal region studied here." (PMID 27070146, 2016). "The first mice that co-expressed humanized APP (MoHuAPPswe) and PS1dE9 mice were produced by crossing mice that independently expressed the genes, and in a re-examination of these animals we document that the frequency of cerebellar amyloid deposits was very low." (PMID 26566997, 2015). "Despite evidence that axonal function can survive a significant degree of dystrophy during amyloidosis and may still recover normal function, it is striking that the APP pathology is most severe in the thalamic PO, which ultimately sustains massive neuronal loss." (PMID 25727649, 2015). "Interestingly, hnRNP A1 up-regulation induces alternative splicing of the amyloid precursor protein (APP) mRNA, which is followed by reduced Aβ levels, suggesting that a fall of the hnRNP A/B protein levels may inversely exacerbate amyloid pathology in the OB." (PMID 26517091, 2015). "Thus, we can conclude that eIF2α phosphorylation does not have a role in Aβ-associated BACE1 and APP elevation, or in amyloid pathology, at least in primary neurons and 5XFAD mice." (PMID 24992504, 2014). "Finally, in the AD-like transgenic model that expresses human APP with familial mutations, suppression of endogenous tau prevented Aβ-dependent water maze learning and memory deficits without reversing the amyloid pathology." (PMID 24416616, 2013). "Therefore, deregulation of APP processing might be an early event in the progression of the AD-like amyloid pathology." (PMID 22472085, 2012). "On the other hand, however, overexpression of FAD-linked mutant APP could lead to olfactory sensory neuron apoptosis in the absence of amyloid plaque, which might be the mechanism of deficits in odor detection, one of the earliest AD symptoms." (PMID 23210692, 2012). "NAA is considered to be a good marker of neuronal viability; its decrease in APP(xPS1) mice might be caused by the intraparenchymal accumulation of Aβ; some reports indicated indeed a negative correlation between amyloid load and NAA levels." (PMID 20953404, 2010). "Because APP overexpression lowers cellular copper and decreased copper levels exacerbates amyloid pathology, we investigated whether the synergistic interplay between sod2 ablation and Alzheimer pathology in Tg2576 transgenics is reflected by lowered brain metal levels." (PMID 17579710, 2007). "In APP/PS1 transgenic mice, KMAI@NPs markedly alleviate neuroinflammation, iron overload, amyloid pathology, and neuronal ultrastructural damage, resulting in significant cognitive improvement." (PMID 41970254, 2026). "As a model of cerebral amyloidosis, the APP/PS1 mouse model was used, which develops amyloid pathology starting at 5–6 months of age." (PMID 39896645, 2025). "In this study, we used 5-month-old APP/PS1 mice, an age known to develop early AD pathologies characterized by increasing amyloid plaque burden and gliosis." (PMID 40831503, 2025). "Aβ is formed from the amyloid precursor protein APP after cleavage by β-secretase and γ-secretase in sequence via the amyloidosis pathway." (PMID 41409784, 2025).